RAP1BL (RAP1B like (pseudogene))
Description:
Probable GTP-binding protein with intrinsic GTPase activity.
Synonyms: hRap1B-retro
Gene: Gene (Ensembl biotype translated_processed_pseudogene) on chromosome 5 (76,173,629 to 76,174,183, reverse strand). Ensembl gene ENSG00000254893.
Subcellular location: Cell membrane; Cytoplasm, cytosol